RN7SL497P (RNA, 7SL, cytoplasmic 497, pseudogene)
Gene: Miscellaneous RNA gene on chromosome 15 (41,191,965 to 41,192,265, reverse strand). Ensembl gene ENSG00000240847.
Homologues: Orthologues: chimpanzee Metazoa_SRP (99% identical), macaque Metazoa_SRP (94% identical), guinea pig Metazoa_SRP (57% identical). Paralogues in human: RN7SL2 (80% identical), RN7SL3 (80% identical), RN7SL1 (79% identical), RN7SL220P (78% identical), RN7SL147P (77% identical), RN7SL278P (77% identical), RN7SL804P (76% identical), RN7SL127P (76% identical), RN7SL145P (76% identical), RN7SL258P (76% identical), RN7SL408P (76% identical), RN7SL444P (76% identical), and 701 more.